CCL2 (C-C motif chemokine ligand 2)
Diseases named in the same sentence as CCL2 in open-access papers (continued):
Sharing a sentence is not in itself a finding about the gene and the disease.
tumor (continued). "Monocyte mobilization from the bone marrow to PDAC appears to be driven by the CCL2/CCR2 chemokine axis, ultimately leading to their differentiation into tumor-associated macrophages (TAMs)." (PMID 37509365, 2023). "The expression of CCL2 in tumor cells had a significant correlation with the expression of TP and membrane type 1-matrix metalloproteinase (MMP)." (PMID 37208442, 2023). "CCL2 is of interest as tumor-associated adipocytes, a major component of the tumor stroma in TNBC, can secrete CCL2 to promote infiltration of other pro-tumoral cells, such as MDSCs, into the TME." (PMID 38022679, 2023). "The recruitment of M-MDSCs is mainly mediated by tumour-expressing C–C motif chemokine ligand 2 (CCL2) in several tumour types, including breast, ovarian, gastric, and colorectal cancer." (PMID 36161514, 2023). "Proinflammatory macrophage-derived LEV exhibit tumor tropism dependent on the CCL2/CCR2 signaling axis and promote drug delivery via SNARE-mediated membrane fusion in contrast to SEV." (PMID 37569508, 2023). "Since CD45+CD11b+Ly6G− populations primarily contain monocytes and macrophages, our results suggest that the CCL2 KO MSCs promote anti-tumor responses via mononuclear myeloid cell-mediated pathways in the TME." (PMID 36672395, 2023). "This led to a higher anti-tumor efficacy than an anti-CCL2 monoclonal antibody alone and was able to significantly inhibit TNBC tumor progression." (PMID 38022679, 2023). "Jia and co-authors found that MSCs express iNOS, CCL2, IL-6, and Cox-2 and recruit macrophages at tumor sites." (PMID 37686315, 2023). "Monocyte chemoattractant protein-1 (CCL2) is an important TAM-associated chemokine, responsible for T cells, macrophages, and dendritic cells infiltration in the tumor microenvironment." (PMID 36776840, 2023). "TAMs recruited by CCL2 also play roles in immune surveillance and can inhibit tumour development and progression." (PMID 37108548, 2023). "The potential role of CCL2 in colorectal carcinogenesis has been demonstrated by a study on ApcMin/+/MCP-1−/− mice model that revealed a reduction in tumor progression induced by local increased cytotoxic T lymphocyte and decreased regulatory T cells activity." (PMID 37760840, 2023). "As a result, FAP-positive CAF acts as a major cell source of C-C motif chemokine ligand 2 (CCL2), which enhances immunosuppression through tumor- and inflammation-promoting myeloid-derived suppressor cells (MDSCs)." (PMID 38313431, 2023). "The results showed that STAT3 induced the promoter activity of CCL2 in tumor cells transfected with the promoter region of CCL2." (PMID 38008713, 2023). "The mechanism by which macrophages infiltrated the TME was through the increase in colony-stimulating factor (CSF1) and chemokine ligand 2 (CCL2) (both involved in macrophage recruitment) in post-treatment MYCN-amplified tumours." (PMID 37887559, 2023). "Here, we have demonstrated that the expression of Notch3 was positively associated with the level of soluble tumor-derived chemotactic factors, such as CSF1, CXCL12 and CCL2, which are chemotactic stimulus for macrophage recruitment." (PMID 36647017, 2023). "The cytokine CCL2, which is identified as highly expressed in diverse tumors, induces mononuclear cells in the blood to migrate to the tumor tissue and transform into TAMs." (PMID 36908706, 2023). "Many conserved interactions involved tumour ligands associated with ER stress, such as APOE, IL11 and CCL2." (PMID 37612508, 2023). "The role of CCL2 in the tumor microenvironment is complex but much evidence points to an immunosuppressive role." (PMID 37602328, 2023). "Clinically, the anti-angiogenic treatment sorafenib—one of the first-line agents to treat HCC—is associated with an increase in TANs that produce CCL2 and CCL17, which can establish immunosuppressive niches within the TME to promote tumor cell survival." (PMID 38139412, 2023).
tumor (continued). "Mechanically, losing β3 integrin in mural cells triggers phosphorylate FAK/HGFR/p65 and upregulation of CXCL1, C–C motif chemokine ligand 2 (CCL2) and TIMP-1, while CCL2 stimulates tumor progression via MAP/ERK kinase 1 (MEK1)-ERK1/2-ROCK2 pathway." (PMID 36906534, 2023). "The mechanism described is that LNMAT1 epigenetically activated tumor cell‐derived CCL2 and enhanced transcription by promoting hnRNPL‐mediated H3K4me3 at the promoter of CCL2, which distinctly recruited macrophages into tumors." (PMID 36599655, 2023). "According to previous similar studies, BC lung metastasis can be promoted by inflammatory monocyte recruitment through CCL2 expression by metastatic tumor cells and the lung stroma." (PMID 37373025, 2023). "Macrophages are recruited in tumor sites by various chemokines such as CSF-1, CCL2, 5, CXCL8, and 12, which are secreted from TME." (PMID 38017494, 2023). "Several reports showed that CCL2 can synergize with bacterial endotoxin to activate macrophages to become tumoricidal and to reduce tumor progression and metastasis." (PMID 36374225, 2023). "CCL2 expression in TAMs was correlated significantly with the histological vessel invasion of tumor cells." (PMID 37208442, 2023). "In summary, our results suggest that tumor cell-derived CCL2 is involved in the recruitment of MSCs to TME." (PMID 36672395, 2023). "Several chemokines derived from tumours (CCL2, CCL5, CCL11, CCL15, CXCL1, CXCL2, CXCL10 and CXCL12) can activate mast cell receptors (CCR2, CCR3, CXCR2, CXCR3 and CXCR4) to induce MC migration." (PMID 37497234, 2023). "In disease states, tissue-resident macrophages and circulating inflammatory monocytes are recruited to the tumor periphery and develop into M0-TAMs under the recruitment of multiple chemokines (CCL2 and CCL5) and cytokines (CSF-1 and VEGF family members)." (PMID 37138860, 2023). "In response to the chemoattractant CCL2, monocytes extravasate from the vasculature into primary tumor sites and are reprogrammed within the tumor microenvironment to limit their cytotoxity." (PMID 37575220, 2023). "Inhibiting the CCL2/CCR2 axis is another reasonable treatment strategy for preventing TAMs from migrating into tumor sites." (PMID 36246629, 2022). "It has been reported that CCL2 can reduce tumor sensitivity to drugs by inhibiting drug-induced apoptosis, antiangiogenesis, and antitumor immunity." (PMID 36077785, 2022). "Consistently, in vitro and in vivo studies have found that cross-linking of TAA-bound IgE initiates a TNF-α/CCL2-mediated monocyte and macrophage pro-inflammatory recruitment feedback loop, to potentiate tumour killing and drive pro-inflammatory polarisation." (PMID 35020853, 2022). "Whereas the enrichment of CCR2+ macrophages has been observed in PDAC after radiotherapy, neutralizing or genetic depletion of CCL2 improves radiotherapy responses and attenuates tumor growth in mouse models." (PMID 36230914, 2022). "Revealed the spatial distribution of the major cell types and CCL2-expressing endothelial cells and fibroblasts, indicating tumor invasion." (PMID 36313703, 2022). "At the beginning of tumor development, monocytes are recruited first by CCL2 into the tumor where they differentiate to pro-inflammatory M1-like macrophages." (PMID 35856032, 2022). "CCL2, also known as monocyte chemotactic protein-1 (MCP-1), has been shown to play critical roles in regulating tumor development and progression." (PMID 35177591, 2022). "For example, CAFs accumulate tumor-promoting immune cells by the activation of multiple pathways such as IL-8, CCL2, stromal cell-derived factor (SDF)-1a/CXCR4, and caveolin-1." (PMID 35327514, 2022). "Tumor cells of various types were reported to release CCL2 resulting in the recruitment of macrophages, thereby supporting tumor progression." (PMID 36230833, 2022).
tumor (continued). "We also assessed the ability of tumor-associated neutrophils to possibly recruit other immune system cells, and evaluated the release of CCL2/MCP-1 and CCL5/RANTES by neutrophils stimulated with MDA-EVs." (PMID 35741003, 2022). "CCL2, also called monocyte chemo attractant protein (MCP)-1, was first identified in 1989 and is described as a “tumor-derived chemotactic factor”." (PMID 35563035, 2022). "Related to this, CCL2 is a primary recruiter of tumour monocyte subsets and CXCL10 is known to be a monocyte recruitment factor." (PMID 35226704, 2022). "Tumor cells additionally facilitate the development of MDSCs by secreting CCL2, CCL12, CXCL5 to attract IMCs into the TME while also secreting growth factors that recruit MDSCs in the bone marrow." (PMID 35345849, 2022). "CCL2 is secreted by a range of tumours and tumour-supporting immune cells and induces the migration of pro-tumoral immune cells such as macrophages, TH2, and regulatory T cells." (PMID 35205725, 2022). "Overall, according to the literature, CCL2 in the TME seems to mainly contributes for tumor progression and metastasis formation." (PMID 36699696, 2022). "It has been shown that the tumor stroma produces chemokine CCL2 to increase the release of CCR2+ inflammatory monocytes that infiltrate to tumor microenvironment." (PMID 36497393, 2022). "A mouse model of MMTV-HER2 infection demonstrated that tumor cells and other myeloid cells from early breast lesions produced CCL2, which attracted macrophages to the site of early breast lesions." (PMID 36403055, 2022). "Further ssGSEA revealed that compared to tumours with low circNEIL3 expression, tumours with high circNEIL3 expression exhibited higher levels of CCL2 and LOX." (PMID 35031058, 2022). "High CCL2 and CCL5 expression was associated with tumor metastasis and poor prognosis in BC patients." (PMID 36438499, 2022). "This remarkable relationship of tumor depth vs. T cell exhaustion also correlates with a gradient of CCL2 within the tumor tissue." (PMID 35757757, 2022). "As a critical activator in inflammation and cancer, NF-κB controls the release of TNF-α, CCL-2, various inflammatory factors, and tumor-related genes." (PMID 35955463, 2022). "As the most well‐studied chemokine, CCL2 was originally identified in 1989 from the culture supernatant of peripheral blood monocytes and tumor cell lines." (PMID 35702353, 2022). "Monocytes/MP are attracted from blood, bone marrow, and spleen to the tumor site thanks to CCL2, CCL5, and CSF-1 produced by the tumors cells, fibroblasts, endothelial cells, and even by the TAM themselves." (PMID 35163420, 2022). "Consistent with our results, our previous study has found that the incomplete RFA is involved in rapid tumor progression and hinders PD-1 blockade immunotherapy due to the production of CCL2 by cancer cells." (PMID 35320940, 2022). "GADCs, along with FGL2 and CCL2 expressed by tumor cells and GAMs, also induce Tregs to suppress anti-tumor responses by inhibiting DC antigen presentation." (PMID 35711434, 2022). "CCL2 is frequently highly abundant in the tumour parenchyma, stroma, and ascites and is secreted by both tumour cells and supporting cells such as TAMs themselves, to drive a positive recruitment feedback loop." (PMID 35020853, 2022). "Tumor cell-derived CCL2 is known to recruit macrophages, which are further reprogrammed to TAMs by milieu with the TME." (PMID 35785026, 2022). "For instance, NK cells recruit type 1 dendritic cells to the tumor and promote T1 cell polarization through the release of CCL2, CCL3, CCL4, CCL5, XCL1, and CXCL8, thus inducing anti-tumoral protection." (PMID 35565420, 2022). "Across serum, conditioned media and both tumor types, four factors are consistently detected: CCL2, CXCL1, CXCL10 and Serpin E1." (PMID 35962398, 2022). "CCL-2 is a chemokine secreted by tumor and stromal cells and mediates recruitment of monocytes and neutrophils, both expressing the receptor CCR2." (PMID 35883641, 2022).
tumor (continued). "Elevated levels of G-CSF, IL-6 and CXCL13, and B cell counts were associated with 4T1 growth, whereas CCL17, CXCL10, total myeloid cells, CCL2, IL-10, CXCL1, and Ly6Cintermediate monocytes were associated with CT26 tumour development." (PMID 35226704, 2022). "Because it had previously been discovered in tumor cells in vitro, CCL2 was originally called a tumor-derived chemokine." (PMID 36403055, 2022). "In this study, we aimed to investigate the roles of tumor cell-derived CCL2 on trastuzumab resistance and overcome the resistance by treatment with the anti-CD40-scFv-linked anti-HER2 (CD40 ×HER2) bispecific antibody (bsAb)." (PMID 35851310, 2022). "Therapeutics that disrupt the CCR2/CCL2 axis have been effective in blocking macrophage infiltration and reducing tumor growth and metastasis in preclinical models of cancer, with variable activity demonstrated in early phase clinical trials." (PMID 33603130, 2022). "CCL2, a CC chemokine, is secreted by CSCs of different tumor types to promote macrophage infiltration." (PMID 35740975, 2022). "In summary, our present study demonstrated that overexpression of HMGA2 in CRC cells facilitated macrophage recruitment and M2 polarization via upregulating STAT3-mediated CCL2 secretion, thus promoting tumor immunosuppression in CRC." (PMID 34976223, 2022). "The tumours contain a high M2 macrophage infiltrate within the pleura and effusion TME, which is linked to high TGFB1 and CCL2 expression." (PMID 35637530, 2022). "CCL2 has also been shown to recruit monocytes and monocytic myeloid-derived suppressor cells (MDSCs), which overcome the anti-tumor immune response and promote cancer stemness." (PMID 35585513, 2022). "These miRNAs directly inhibited CCL2 expression in oral cancer and colorectal carcinoma cells, promoting tumor suppression by reducing TAM recruitment and polarization." (PMID 36248881, 2022). "CCL2 recruits Tie2-receptor-expressing macrophages that facilitate the trafficking of tumor cell along aligned collagen fibers toward the endothelium where tumor cell dissemination occurs." (PMID 35267548, 2022). "CCL2 or MCP-1 is a member of the CC chemokine family, and abnormally expressed CCL2 is closely associated with CNS diseases, neoplastic diseases, and inflammatory diseases." (PMID 37008043, 2022). "Pro-inflammatory macrophages and MDSC are first recruited into the tumor by CCL2, which is followed by the infiltration of CD8+ effector and CD4+ helper T cells and eventually accumulation of regulatory T cells." (PMID 35856032, 2022). "Functionally, CCL2 is involved in modulating tumor cell growth by regulating the infiltration of macrophages into tumors, promoting osteoclast maturation, and suppressing cytotoxic lymphocytes in PCa." (PMID 35406450, 2022). "MDSCs can be also be recruited to the tumor microenvironment by CAFs via CCL2, thereby suppressing CD8 T cell proliferation and IFN-γ production." (PMID 36010899, 2022). "Once myeloid cells infiltrate the tumor, they can further produce the cognate ligand CCL2 and maintain or even augment monocyte trafficking into tumors." (PMID 33603130, 2022). "Soluble mediators from cancer cells and stromal cells such as Cxcl1, Ccl2, Vegf family, Tgf‐β and GM‐CSF are reported to participate in tumour development." (PMID 35170261, 2022). "LncRNA LNMAT1 can modulate the tumor microenvironment (TME) in lymphatic metastasis of BLCA by upregulating the expression of CCL2 and recruiting macrophages into the tumor." (PMID 36531246, 2022). "Tumor cells can actively attract circulating monocytes to the tumor site by secreting CCL2, and then the recruited monocytes developed into TAMs through granulocyte-macrophage colony-stimulating factor (GM-CSF) and macrophage colony-stimulating factor (MCSF)." (PMID 36300110, 2022).
tumor (continued). "In the radioresistant pancreatic ductal adenocarcinoma (PDAC) model, tumour-derived CCL2 was significantly upregulated, resulting in increased infiltration of inflammatory monocytes and macrophages but not T cells." (PMID 35365161, 2022). "CCL2, in addition to being a strong chemoattractant, can protect monocytes against apoptosis in the tumor microenvironment by upregulating anti-apoptotic proteins and inhibiting caspase-8 cleavage." (PMID 35053248, 2022). "The CCL2/CCR2 signal pathway plays an essential role in monocyte recruitment toward the tumor niche." (PMID 35600367, 2022). "We did not see significantly increased CCL2 levels in plasma of mice with delayed-growth tumor compared with mice with rapid-growth tumor, even though mice with delayed-growth tumors had significantly elevated levels of CCL2 compared with tumor naive mice." (PMID 35503656, 2022). "In MDA-MB-231 cells, CCL2 gene silencing led to inhibition of CCL2 expression, which—in turn—led to the significant inhibition of tumor growth, cell proliferation, and increased necrosis." (PMID 35955463, 2022). "Recruitment and differentiation of TAM macrophages at tumor sites are mainly induced by granulocyte–macrophage colony-stimulating factor (GM-CSF), CCL2, VEGF, IL-6, and IL-8, which are related to hypoxia, acidity, and inflammation of tumor tissues." (PMID 36209263, 2022). "CCL2 is secreted by activated macrophages, fibroblasts, vascular smooth muscle, lymphocytes, and tumor cells." (PMID 36699696, 2022). "Resident and infiltrating TAMs are recruited to the growing tumor in response to a variety of tumor-secreted cytokines, including CCL2, GM-CSF, EGF, CXC3CL1, SDF-1, and CSF-1." (PMID 35885058, 2022). "Monocytes are recruited around tumor tissue and differentiated into macrophages through the combination of CCR2 on its surface and chemokine CCL2 (synthesized by tumor cells or other cells), which together form TME with other components." (PMID 36611857, 2022). "CCL2 mediates tumor cell metastasis by binding to CCR2 on tumor cells and induces the expression of matrix metalloproteinase-9 (MMP-9) to increase the invasiveness of tumor cells." (PMID 35320940, 2022). "CCL2 promotes tumor progression by recruiting TAMs, but TAMs also induce cancer resistance by secreting CCL2." (PMID 36077785, 2022). "Macrophages are a major component in the tumor microenvironment arising from spinal marrow-derived monocyte differentiation in response to CC chemokine 2 (CCL2/CCR2) and colony-stimulating factor 1 (CSF-1/CSF-1R)." (PMID 36246916, 2022). "For example, HIF induces the expression of CCL2 in pancreatic ductal adenocarcinoma cells, which induces the recruitment of macrophages to the tumor." (PMID 35565420, 2022). "RAB42 transcriptional expression was positively correlated with immune chemokines such as CCL22 and CCL2, which can be secreted by tumor cells to recruit the Tregs and TAMs respectively into the TME." (PMID 35720121, 2022). "Of all chemokines assayed, the CCR2/CCR4 ligand CCL2 was the most abundant chemokine detected in tumour biopsy, CUSA and cultured GNS cell supernatants, and was present above the limit of detection in all samples analysed." (PMID 35464424, 2022). "These genes encode for chemokines (CCL2/MCP-1; CX3CL1/Fractalkine; CCL7/ MCP-3) that modulate the immune response but have also frequently been found to be enriched in the tumor microenvironment." (PMID 35661927, 2022). "SU4312 also improves the anti-tumor immune microenvironment, which presumably results from the down-regulation of CCL2 due to the inhibition of YAP." (PMID 36013004, 2022). "Tumor cells release chemoattractant proteins that recruit GAMs, such as CCL2, colony stimulating factor-1 (CSF-1), granulocyte–macrophage colony stimulating factor, hepatocyte growth factor or scatter factor, stroma-derived factor 1 (SDF-1), and GDNF." (PMID 35448036, 2022).